CDKN2A (cyclin dependent kinase inhibitor 2A)
Diseases named in the same sentence as CDKN2A in open-access papers (continued):
Sharing a sentence is not in itself a finding about the gene and the disease.
breast carcinoma (continued). "Only SLC31A1, but not CDKN2A, was negatively related to a favorable overall survival in breast cancer." (PMID 37884650, 2023). "For CDKN2A, no statistical difference of overall survival was found between lower group and higher group in breast cancer." (PMID 37884650, 2023). "In particular, no statistical prognostic value of CDKN2A in breast cancer was observed, while patients with higher expression of SLC31A1 displayed a poor prognosis." (PMID 37884650, 2023). "Further in vitro and in vivo studies are required to support the involvement of CDC20B, HSD3B1, and CDKN2A, as possible prognostic biomarkers of non-steroidal AI resistance in breast cancer." (PMID 37415453, 2023). "Cadherin 1 (CDH1), CDKN2A, the runt‐related transcription factor 3 (RUNX3), BRCA1 and RASSF1A are reported to be suppressed by DNMT3B‐dependent DNA hypermethylation in gastric or breast cancers." (PMID 34133843, 2022). "We analyzed the expression pattern of CRGs in breast cancer tissues and non-tumor tissues based on TCGA and GTEx dataset, illustrating that CDKN2A, DLD, DLAT, MTF1 and PDHB expression were significantly elevated in breast cancer compared with their normal tissues." (PMID 36518756, 2022). "Nonetheless, CDKN2A expression was significantly up regulated KICH and breast cancer (BRCA)." (PMID 36581992, 2022). "Another vital discovery of our research was that we developed a cuproptosis-related prognostic signature containing six genes (CDKN2A, MTF1, PDHA1, DLD, LIPT1, and FDX1) for breast cancer, which predicted the OS rate with an accuracy that ranged from medium to high." (PMID 36312586, 2022). "For example, CDKN2A, NF1, and NBN were associated with increased risk for breast cancer in the current study, but were not significant in previously published analyses in our smaller cohorts." (PMID 31406321, 2020). "At gene level, AA women with breast cancer showed higher expression of several key cell cycle regulating genes, including CCNE2, CCNB1, CCNA1, CDKN2A and other tumor related genes CRYBB2, TMPO, AMFR, PSPHL, which directly impact the development and aggressiveness of tumors." (PMID 32824813, 2020). "We determined whether some of the commonly silenced breast cancer tumor suppressor genes were differentially expressed in the mammary tumors between control and HF offspring, specifically BRCA1, CDKN2A, and PTEN." (PMID 31889127, 2019). "In agreement with a negative role of CDKN2A in CIC formation as proposed above, p16INK4a expression was inversely correlated with CIC frequency in human breast cancers." (PMID 29904067, 2018). "Five further patients (5 of 83; 6% of cohort) were found to harbor pathogenic variants in genes lacking a firm association with breast cancer susceptibility to date (i.e., Fanconi pathway genes, RECQ family genes, CDKN2A/p14ARF, and RUNX1)." (PMID 30086788, 2018). "p16 is lost in about 30% of breast cancers, mainly as a result of genetic or epigenetic inactivation of CDKN2A, but its prognostic value in these cases has not been fully demonstrated." (PMID 28445153, 2017). "The present study provides methylation levels for the promoters of APC, BRCA1, CDKN2A, ESR1, ESR2, HER2/neu and PTEN, CDKN2A exon 2 and LINE-1 in tumor, tumor-adjacent and tumor-distant tissues from 18 breast cancer patients and normal breast tissues from four healthy women." (PMID 28403857, 2017). "mRNA, protein and methylation status of CDKN2A and MTAP in the breast cancer cell lines." (PMID 26751376, 2016).
breast carcinoma (continued). "Methylation-sensitive high-resolution melting was used to screen promoter methylation in a panel of 13 genes reported as methylated in breast cancer (RASSF1A, TWIST1, APC, WIF1, MGMT, MAL, CDH13, RARβ, BRCA1, CDH1, CDKN2A, TP73, and GSTP1) in 29 tumour pairs (16 ipsilateral and 13 contralateral)." (PMID 26452468, 2015). "The direct co-culture studies revealed the up-regulation of CDKN2A, a cell cycle regulator, and GSTP1, a gene responsible for the detoxification of drugs, which have been shown to be up-regulated in multi-drug resistant breast cancer." (PMID 24176089, 2013). "The CDK4/6 specific inhibitors palbociclib (breast cancer phase III trial NCT01942135), ribociclib (melanoma phase II trial NCT01719380), and abemaciclib (breast cancer phase Ib trial NCT02057133) all potently inhibit CDK4/6 and are potentially useful in acute leukemias with CDKN2A/B alterations." (PMID 40247105, 2025). "Importantly, the lack of consistent subtype-specific methylation patterns in breast cancer cell lines highlights the need for a deeper understanding of CDKN2A silencing mechanisms." (PMID 40649906, 2025). "MAGEA2, MAGEA3, MAGEA4, MAGEA6, and MAGEA12 are up-regulated in the CDKN2A alteration group, amongst which MAGEA3 (HR=1.61[1.27-2.04], p=8.2e-5), MAGEA4 (HR=1.38[1.08-1.77], p=0.011), and MAGEA12 (HR=1.65[1.10-2.48], p=0.015) are accompanied by worse prognosis in breast cancer." (PMID 37857018, 2023). "In breast cancer, lncRNA ANRIL induces gene silencing at the INK4b-ARF-INK4a locus by interacting with CBX7 (PRC1 component) and SUZ12 (PRC2 component) and regulates its adjacent tumor suppressor CDKN2A/B through epigenetic mechanisms, thereby controlling cell proliferation and senility." (PMID 35397764, 2022). "Copy number aberrations (CNAs) in known breast cancer driver genes present in the PDTXs included gains/amplifications of MYC (78%), CCNE1 (34%), ZNF703 (25%), CCND1 (31%), MDM2 (25%), and ERBB2 (9%) and deletions of PTEN (41%), PPP2R2A (72%), CDKN2A (47%), and CDKN2B (47%)." (PMID 27641504, 2016). "In addition, deletion in the gene for CDKN2A (Cyclin-Dependent Kinase Inhibitor 2A), capable of inducing cell cycle arrest in the G2 phase and apoptosis by preventing the activation of cyclin B1/CDC2 complexes, and acting as a tumor suppressor in breast cancer, is common in HBCX-17 and T174 cells." (PMID 38786044, 2024). "This study analyzed the methylation statuses of CDKN2A/p16INK4A and RB1 genes in the tumor, non-tumor tissue, and cfDNA of breast cancer patients." (PMID 38716944, 2024). "No drugs targeting CDKN2A/B have been approved, while CDK4/6 inhibitor paboxilin has been proved in breast cancer by FDA." (PMID 27974690, 2016). "In addition, the possible ferroptosis mechanisms of CDKN2A, PSAT1, SLC7A11, LAMP2, CAV1, and HMGB1 in TNBC and ASNS, ZFP69B, ELAVL1, TF, HELLS, and DPP4 in breast cancer have not been reported." (PMID 36568247, 2022).
breast carcinoma (continued). "However, zebrafish are not mammalian, so some important pathways in breast cancer tumor development are absent, including BRCA1, p16 (CDKN2A), Leukemia Inhibitory Factor (LIF), oncostation M (OSM) and interleukin 6 (IL6)." (PMID 34123857, 2021).
glioblastoma (252 papers, 1997 to 2026). The most malignant astrocytic tumor (WHO grade IV). "Subsequently, an integrated analysis of CDKN2A/B loss and additional molecular glioblastoma hallmarks was conducted." (PMID 41438586, 2026). "Of the three TERT wildtype glioblastomas, one case (33%) showed CDKN2A/B loss while two cases (66%) showed retained CDKN2A/B." (PMID 41438586, 2026). "Loss of CDKN2A/B was found 44% (20/45) of all glioblastomas, thereby, in 46% (6/13) of RTK I, 67% (10/15) RTK II, and 24% (4/17) of MES." (PMID 41438586, 2026). "Of all 39 TERT mutated glioblastomas, 17 tumors (44%) showed CDKN2A/B loss and 22 tumors (56%) showed retained CDKN2A/B." (PMID 41438586, 2026). "CDKN2A/B loss was found in six of thirteen glioblastomas of RTK I subtype (46%), in ten of 15 glioblastomas of RTK II subtype (67%), and in four of 17 glioblastomas of MES subtype (24%)." (PMID 41438586, 2026). "ITSS grades 2–3 were linked to glioblastomas (p < 0.001), necrosis (p < 0.001), microvascular proliferation (p < 0.001), and CDKN2A/B homozygous deletions (p = 0.02)." (PMID 40507765, 2025). "On multivariable CPH analysis incorporating significant clinical variables, CDKN2A/B loss was the only genetic co-alteration that remained significantly associated with worse OS in NF1-mutant glioblastoma." (PMID 40985888, 2025). "Among the variants found in the tumor, CDKN2A/B HD occurs in around 50% of epithelioid glioblastoma, and pTERT mutations are also common." (PMID 41331048, 2025). "NF1 alteration (HR: 1.28), PIK3CA/3R1 alteration (HR: 1.25), CDKN2A/B loss (homozygous or heterozygous, HR: 1.21), and increasing age (HR: 1.03) negatively impacted survival for glioblastoma." (PMID 39164213, 2025). "Previous studies have reported that the homozygous deletion of CDKN2A is associated with high-grade disease, particularly glioblastoma, and CDKN2A/B risk variants appear to have a general effect on tumor risk." (PMID 39457569, 2024). "Loss of CDKN2A function has been associated with uncontrolled cell proliferation, decreased response to chemotherapy, and poor prognosis in glioblastoma patients." (PMID 38438773, 2024). "One gene that has attracted considerable attention in glioblastoma research is CDKN2A, which encodes multiple tumor suppressor proteins involved in cell cycle regulation and senescence." (PMID 38438773, 2024). "Our findings demonstrate that CDKN2A downregulation in glioblastoma cells is associated with decreased cell viability, enhanced drug resistance, increased self-renewal capacity, and altered expression of pluripotency markers." (PMID 38438773, 2024). "While pemetrexed use in glioblastoma is unexplored, CDKN2A and MTAP loss have emerged as important predictors of pemetrexed benefit in other cancers." (PMID 38187871, 2024). "Genetic alterations affecting CDKN2A, such as homozygous deletions, point mutations, or promoter methylation, have been identified in various cancer types, including glioblastoma." (PMID 38438773, 2024). "To investigate the underlying mechanism of CDKN2A downregulation in U87 glioblastoma cells, we analyzed the CpG islands in the CDKN2A gene promoter and performed methylation-specific PCR (MSP) assays." (PMID 38438773, 2024). "Only one of the de novo RRD glioblastomas had CDKN2A/B homozygous deletion (1/9, 11%), with another tumor harboring a truncating frameshift mutation in CDKN2A that was a rare mechanism of CDKN2A gene inactivation in the conventional glioblastomas (11/450, 2%)." (PMID 38079020, 2023). "Another study was focused on the CDKN2A gene, which encodes the p16INK4a protein, often inactivated in glioblastoma." (PMID 38003512, 2023).
glioblastoma (continued). "In this regard, it is known that activation of the epidermal growth factor receptor (EGFR) correlates with Cdkn2a loss in glioblastoma formation." (PMID 37063827, 2023). "Our case showed multiple chromosomal gains and losses including a gain of chromosome 7, loss of chromosome 10 and CDKN2A/B homozygous deletion, a constellation typically present in glioblastoma/gliosarcoma, IDH-wildtype." (PMID 36520193, 2023). "PIK3CA mutations and combined EGFR, PTEN, and CDKN2A alterations conferred worse prognosis in some IDH-wildtype glioblastoma subsets." (PMID 32640746, 2020). "These CIMP-, IDHwt subtypes (MES, RTK I and RTK II) exhibited the classic glioblastoma copy number alterations (CNAs) consisting of gain of chromosome 7, loss of chromosome 10 and focal CDKN2A/B deletion." (PMID 33339831, 2020). "For comparison, the U-87MG cell line represents glioblastoma hypodiploid cells derived from a primary brain tumor and carries several mutations (i.e., CDKN2A, RAS, PTEN, HF1 and PCM1)." (PMID 31195298, 2019). "As such, homozygous CDKN2A/B loss is likely a second event in the tumorigenesis of IDH-wildtype astrocytoma or glioblastoma." (PMID 29616301, 2018). "Amongst IDH-wildtype astrocytomas/glioblastomas, one of the most frequent alterations is a homozygous loss of CDKN2A and CDKN2B." (PMID 29616301, 2018). "Amplification of EGFR or MDM2, PTEN mutation as well as homozygous CDKN2A or p14ARF deletions are all rare in secondary glioblastomas." (PMID 19333441, 2009). "One glioblastoma with hemizygous deletion of CDKN2A showed a missense mutation in exon 2 (codon 83) that would result in the substitution of tyrosine for histidine in the protein." (PMID 9000591, 1997). "Glioblastomas with retention of both alleles of CDKN2A (14 tumours) and CDKN2B (16 tumours) expressed transcripts for these genes." (PMID 9000591, 1997). "In addition, our research has revealed that CDKN2A/B loss is a phenomenon that occurs predominantly in glioblastoma of the molecular subgroup RTK II." (PMID 41438586, 2026). "A novel promising biomarker in glioblastoma therapy may now be the detection of chromosomal loss of CDKN2A/B." (PMID 41438586, 2026). "They suggested that CDKN2A deletion could remodel the distribution of polyunsaturated fatty acids into different lipid compartments, sensitizing glioblastomas with CDKN2A loss to lipid peroxidation and ferroptosis both in vitro and in vivo." (PMID 39457569, 2024). "However, the precise mechanisms underlying CDKN2A dysregulation and its functional significance in glioblastoma remain incompletely understood." (PMID 38438773, 2024). "Besides, the tumor showed multiple copy number alterations including gain of chromosome 7, loss of chromosome 10 and homozygous deletion of CDKN2A/B, typically seen in glioblastoma/ gliosarcoma, IDH-wildtype." (PMID 36520193, 2023). "CDKN2A mutations are associated with Glioblastoma development." (PMID 35538578, 2022). "Among the top-ranked features indicative of poor prognosis are: increased age at diagnosis (rank 3); histologic classification as de novo grade IV glioblastoma (rank 5); loss of chromosome arms 10p and 10q (ranks 2, 4); and deletions of tumor suppressor genes CDKN2A and PTEN (ranks 1, 8)." (PMID 28916782, 2017).
glioblastoma (continued). "The genomic profiling of the GB samples included in our study confirmed the presence of common glioblastoma alterations reported in previous studies: loss/partial loss of chromosome 10, polysomy of chromosome 7, focal deletion of the CDKN2A/B and focal high-level amplifications of EGFR." (PMID 25940437, 2015). "In a series of 46 glioblastomas, 16 anaplastic astrocytomas and eight astrocytomas, all tumours retaining one or both alleles of CDKN2A (48 tumours) and CDKN2B (49 tumours) were subjected to sequence analysis (entire coding region and splice acceptor and donor sites)." (PMID 9000591, 1997). "Research has indicated that the loss of the CDKN2A gene alters the lipid composition of glioblastoma multiforme (GBM), rendering GBM cells sensitive to lipid peroxidation and ferroptosis." (PMID 38612764, 2024). "Thus, recurrent glioblastoma shows a higher frequency of copy number variations in several genes, particularly cell cycle genes, an enrichment in the cyclin-dependent kinase inhibitor 2A/B (CDKN2A/B) loss, and an excessive activation of cell cycle pathway genes." (PMID 33585240, 2020). "Recently, it was shown with the use of knockout mice for Cdkn2a/2b and/or Pten that DNA double-stranded breaks cooperate with the loss of Ink4 and Arf (protein products from Cdkn2a/2b after alternative splicing) tumor suppressors to generate glioblastomas with frequent c-Met amplification." (PMID 25221514, 2014). "In this study, an integrated analysis of CDKN2A/B chromosomal deletion was performed in 45 glioblastomas with IDH wildtype, and the results were correlated with the molecular subtypes of RTK I, RTK II, and MES." (PMID 41438586, 2026). "Despite these morphological differences, both cases matched the methylation class "Glioblastoma, IDH-wildtype, mesenchymal subtype" and shared molecular features typical of glioblastoma, including chromosome +7/-10 and CDKN2A/B deletion." (PMID 42158566, 2026). "The analysis of CDKN2A/B status was conducted on all 45 glioblastomas, employing the method of relative probe intensity." (PMID 41438586, 2026). "Of all 26 MGMT methylated glioblastomas, twelve showed CDKN2A/B loss while 14 showed retained CDKN2A/B, and of all 19 MGMT unmethylated glioblastomas eight showed CDKN2A/B loss while 11 showed retained CDKN2A/B." (PMID 41438586, 2026). "Second, we utilized freshly-resected murine glioblastoma-like cells isolated from tumors induced by RCAS-PDGAB lentivirus injection into Nestin-Tva/Cdkn2a-/- mice." (PMID 39773984, 2025). "In glioblastoma, alterations in CDKN2A/B and PDGFRA were significantly enriched in patients ≥65 years old while there was a depletion of these alterations in patients between 40 and 64 years old." (PMID 39164213, 2025). "We did not provide further information on patients with pathological grade 4 astrocytoma, specifically IDH‐mutant glioblastoma, or patients with molecular grade 4 astrocytoma with CDKN2A/B homozygous deletion." (PMID 38970209, 2024). "To investigate the expression levels of CDKN2A in glioblastoma cells, we performed quantitative reverse transcription PCR (qRT-PCR) analysis." (PMID 38438773, 2024). "The observed upregulation of these cell cycle regulators provides mechanistic insights into the tumor-suppressive function of CDKN2A in glioblastoma." (PMID 38438773, 2024). "In this study, we aimed to investigate the functional significance and regulatory mechanisms of CDKN2A in glioblastoma." (PMID 38438773, 2024). "CDKN2A inhibition resulted in enhanced sphere-forming ability, a characteristic feature of glioblastoma stem cells (GSCs) that contribute to tumor initiation and recurrence." (PMID 38438773, 2024).